AZGP1 (alpha-2-glycoprotein 1, zinc-binding)
Diseases named in the same sentence as AZGP1 in open-access papers (continued):
Sharing a sentence is not in itself a finding about the gene and the disease.
cancer (continued). "Using mass spectrometry, we identified that a subset of TNBC cells secreted zinc-alpha-2-glycoprotein, ZAG/AZGP1, an adipokine previously linked to adipocyte lipolysis and cancer cachexia." (PMID 38888911, 2024). "Together, these results suggest that AZGP1 works in part through constraining cancer progression though inhibiting angiogenesis in human PCa." (PMID 38659028, 2024). "Lenvatinib, an FDA-approved anti-cancer small chemical inhibitor of multiple tyrosine kinases, induced AZGP1 expression in cholangiocarcinoma where it led to the suppression of TGF-β1-induced EMT." (PMID 38675493, 2024). "Given the limited investigations into the mechanisms through which AZGP1 affects cancer behavior, its role remains poorly defined." (PMID 38659028, 2024). "In this study, we found that AZGP1 was the key target of lenvatinib in ICC, and its low expression in ICC cancer tissues was associated with a poor prognosis in patients." (PMID 37669935, 2023). "In conclusion, our study revealed that AZGP1 is the key target of lenvatinib in ICC, and its low expression in ICC cancer tissues is associated with a poor prognosis in patients." (PMID 37669935, 2023). "And though there was little research in BLCA, there were a series of researches indicating the role of AZGP1 in various cancers." (PMID 36591526, 2022). "AZGP1 has been demonstrated to inhibit cancer cell proliferation and invasion by inhibiting TGF-β-mediated epithelial–mesenchymal transition, based on which was recognized as a tumor suppressor." (PMID 36553191, 2022). "AZGP1 has been suggested as a modifier of metabolic functions, insulin sensitivity, fat mass expansion, blood pressure regulation, cancer progression, inflammatory disease, vitiligo, neurological disease and cardiovascular (CV) disease." (PMID 34083628, 2021). "AZGP1, an important protein involved in insulin sensitivity and plays a role in metabolism and cell cycle, which are known to be altered in cancer progression." (PMID 33564003, 2021). "AZGP1, BPIFB2 and KLK1 were significantly downregulated in our data of which role of KLK1 and AZGP1 is well reported in cancer but BPIFB2 remains unexplored." (PMID 33564003, 2021). "Abnormally high expression of AZGP1 in CRC tissues with liver metastasis indicated that it correlated with cancer metastasis." (PMID 31632499, 2019). "Numerous studies show the activation of FLNA is directly related with oncogenesis and metastasis in different cancers, we assumed that AZGP1 promoted cancer development and metastasis mediated by FLNA." (PMID 31632499, 2019). "AZGP1 expression has, in general, been reported as downregulated in certain carcinomas, including those in the breast, prostate, liver, and stomach." (PMID 31632499, 2019). "AZGP1 is a multifunctional protein involved in lipid mobilization, lipolysis, immunoregulation and cancer cachexia." (PMID 28160560, 2017). "Selected targets were confirmed by immunohistochemistry: NPY and PLA2G7 (up-regulated in ERG+ cancers), and AZGP1 and TFF3 (down-regulated in ERG+ cancers)." (PMID 23390522, 2013). "Recently, it has been shown that AZGP1 plays a crucial role in carcinogenesis and is of clinicopathologic significance in human cancers." (PMID 22625427, 2012). "The impact of AZGP1 promoter methylation on tumors has been reported in other cancers." (PMID 41535762, 2026). "AZGP1 has been shown to inhibit the TGF-β pathway in cancer." (PMID 41366520, 2026). "Zinc-alpha-2-glycoprotein (ZAG/AZGP1), which is called lipid-mobilizing factor, is structurally similar to human leukocyte antigen class I. AZGP1 is a critical protein involved in various physiological processes, including lipid metabolism, immune response, and cancer progression." (PMID 40900789, 2025). "While many prognostic biomarkers play roles in cancer progression, such as by driving proliferation or metastasis, the role of AZGP1 in cancer aggressiveness remains unclear for PCa." (PMID 38659028, 2024).
cancer (continued). "AZGP1 is also lost in other cancers, enabling TGF-β1-induced EMT." (PMID 38675493, 2024). "In addition, AZGP1 acted as a classical lipid mobilization factor and promoted the development of cancer cachexia." (PMID 38245780, 2024). "AZGP1 has been recognized as a crucial promoter in cancer metastasis and lipid metabolism." (PMID 39731080, 2024). "Thereafter, TRIM25 knockdown led to AZGP1 upregulation and induced cancer cell apoptosis." (PMID 38183356, 2024). "The possibility of AZGP1 as a biomarker in various carcinomas has been suggested." (PMID 38183356, 2024). "AZGP1 expression in cancer tissues was significantly lower than that in paracancerous tissues." (PMID 37669935, 2023). "AZGP1 has been reported to be a key promoter of cancer metastasis and lipid metabolism." (PMID 37696831, 2023). "Given the inhibitory effect of DIS3L2 KD in cell viability, we explored a potential target of DIS3L2 among genes that clustered in the mTOR pathway, and we found AZGP1, whose mTOR inhibitory activity has been previously documented in different cancer types, including CRC." (PMID 37340282, 2023). "The AZGP1 gene plays a fundamental role in lipid metabolism and other metabolic diseases such as cancer, being considered as a lipid-metabolizing factor that impacts the fatty acid metabolism, increasing the lipolysis process and decreasing the inflammation signs." (PMID 35804531, 2022). "However, the reduction in levels of AZGP1 in cancer patients mandates a very sensitive detection method for it to be successful as a tumour marker in clinical practice." (PMID 33564003, 2021). "Currently, abnormal expression of AZGP1 can be used as an important indicator for prognosis, however, the mechanism in cancer progression remains largely unknown." (PMID 31632499, 2019). "Also, AZGP1 was identified as a potential predictive biomarker for cancer and can be used for early diagnosis." (PMID 31632499, 2019). "Zinc-α2-glycoprotein 1(AZGP1) is a candidate biomarker for diagnosis and prognosis in cancer." (PMID 31632499, 2019). "Zinc-α2-glycoprotein (ZAG, also known as AZGP1), a newly identified adipokine, was initially shown to be a tumor-derived molecule responsible for loss of fat mass in patients with cancer cachexia through its action as a lipid-mobilizing factor." (PMID 29467670, 2018). "Serum levels of AZGP1, best known as a marker in cancer progression, were demonstrated in a small study to be increased in the early phase of AKI, and high initial levels of AZGP1 correlated with extra-renal complications but not with parameters of renal function." (PMID 26104320, 2015). "In mice with cancer cachexia the expression of AZGP1 was up-regulated suggesting that AZGP1 might act as a cancer cachexia factor." (PMID 23849457, 2013). "These study results support the hypothesis that AZGP1 may serve as a tumor suppressor in some cancers." (PMID 23935945, 2013). "Interestingly, expressions of AZGP1 in cancer tissues have been demonstrated to be connected with recurrence and metastasis." (PMID 22625427, 2012). "Interestingly, complicated relationships between AZGP1 expression and clinical stages of cancer patients are common." (PMID 22625427, 2012). "As the structure and sequence are highly homology to MHC class I, AZGP1 may afford some protective effect in tumor patients and benefit to prevent the cancer progression." (PMID 22625427, 2012). "Furthermore, in a series of cancer types, AZGP1 has been shown to function as a tumor suppressor." (PMID 41366520, 2026). "Studies have shown that AZGP1 may serve as a prognostic marker for several cancer types." (PMID 37669935, 2023). "AZGP1 knockdown prevented cancer cell EMT, which could contribute to the inhibition of metastasis." (PMID 31632499, 2019). "We propose that AZGP1 might play an important role in the process of malignant transformation in colon mucosa cells and/or in survival or maintenance of malignant transformed cancer cells." (PMID 25561225, 2014).
cancer (continued). "EHMT2 inhibition enhanced NK cell-mediated cytotoxicity by upregulating AZGP1 and NKG2D ligands, reducing TGF-β1 levels in cancer cells, and relieving TGF-β1-mediated suppression of NK cell function and migration." (PMID 41366520, 2026). "Similar to UNC0642 and A366, BRD4770 treatment of cancer cells enhanced their NK cell-mediated cytotoxicity (Fig. EV8A), stimulated the expression of AZGP1 (Fig. EV8B,C), and suppressed the expression of TGF-β1 (Fig. EV8D,E)." (PMID 41366520, 2026). "Zinc-alpha 2-glycoprotein (AZGP1) is a serum protein with postulated functions in metabolism, cancer and cardiovascular disease." (PMID 34083628, 2021). "Zinc-α2-glycoprotein (AZGP1), Flotillin-2 and Protein/nucleic acid deglycase DJ-1 (PARK7) were proposed as biomarkers for cancer diagnosis." (PMID 30158500, 2018). "Consistent with the available literature in other cancer subtypes, both qRT-PCR and IHC analyses demonstrated that STS patients with metastasis or shorter overall survival had lower AZGP1 levels." (PMID 29357838, 2018). "As can be inferred from the array signal intensity levels, expression of the major functional prostatic secretory proteins ACPP, AZGP1, KLK2, KLK3, and MSMB was down-regulated in the cancer cells compared to the luminal cells." (PMID 20021671, 2009). "Since TGF-β1 can promote immune evasion by acting on both cancer cells and NK cells, we asked if the conditioned media collected from EHMT2 inhibitor-treated cells or AZGP1- and TGF-β1-expressing cells could influence NK cell-mediated cytotoxicity." (PMID 41366520, 2026). "We demonstrate that downregulation of AZGP1 does not impact cancer cell proliferation, migration, or invasion in PCa." (PMID 38659028, 2024). "In contrast to ANPEP, AZGP1, the six metallothioneins and the network HUB genes, only one of the zinc-transporters (SLC39A1 - upregulated) showed any consistent differential expression between high- and low-grade cancer samples." (PMID 35707723, 2022). "Long intergenic non-protein coding RNA, LINC01426, promotes cancer progression via AZGP1 and predicts poor prognosis in patients with LUAD." (PMID 33672117, 2021). "AZGP1 might also inhibit tumor invasion by suppressing TGF-β-mediated epithelial-to-mesenchymal transition, which plays a critical role in cancer progression." (PMID 29357838, 2018). "Importantly, the fact that we did not detect any mRNA of cancer‐specific genes (AZGP1 and KRT19), nor of CAF‐specific genes (LUM and DCN), confirmed the absence of non‐endothelial RNA contamination." (PMID 40348600, 2025). "For patients treated by focused radiation, the cancer markers but not ACPP, AZGP1, KLK3 would be lost if the tumor is successfully ablated." (PMID 23029164, 2012). "The signature highlights genes AZGP1, ANPEP and metallothioneins with zinc-binding properties not previously studied in the prostate, and the expression of these genes are reduced in more aggressive cancer lesions." (PMID 35707723, 2022).
tumor (73 papers, 2006 to 2026). "The results indicated that loss of AZGP1 expression led to elevation of the glycolytic pathway, promoting tumor proliferation and metastasis." (PMID 41535762, 2026). "Utilizing multiple datasets, including GSE21034, DKFZ2018, and TCGA-PRAD cohorts, we compared the expression levels of AZGP1 across different T stages, N status, Gleason scores, and tumor mutation burdens (TMB)." (PMID 41535762, 2026). "The mechanisms underlying AZGP1’s effects on the prostate normal and tumor microenvironment are unclear." (PMID 38659028, 2024). "This was well in concordance with its proposed role of tumor suppressor, backed up primarily by gene expression studies where low expression of AZGP1 is associated with a higher risk of aggressive time-dependent outcomes in PCa." (PMID 36553191, 2022). "The down-regulation of AZGP1 was reported to be associated with histone acetylation and thought to promote tumor progression through PTEN/Akt and CD44s pathways." (PMID 32636408, 2020). "MIIP downregulation stimulates tumour cells to secrete glycosylated AZGP1 protein, which acts on adipocytes to activate the intracellular cyclic adenosine monophosphate (cAMP)-PKA signalling pathway-subsequently inducing adipocyte browning and lipolysis." (PMID 41498391, 2026). "In summary, promoter methylation of AZGP1 leads to reduced transcriptional expression, thereby promoting glycolysis in tumor cells and facilitating metastasis." (PMID 41535762, 2026). "Promoter methylation of AZGP1 leads to reduced transcriptional expression, thereby promoting glycolysis in tumor cells and facilitating metastasis." (PMID 41535762, 2026). "Knockdown of AZGP1 was carried out in the 22RV1 line, and the migration and invasion capacity of tumor cells in Transwell assays were significantly enhanced after knockdown of AZGP1." (PMID 41535762, 2026). "Metabolic analysis of single-cell data reveals that tumor cells with lower AZGP1 expression exhibit significantly higher glycolytic capacity." (PMID 41535762, 2026). "AZGP1 thus serves as a biomarker for predicting metastasis, with low AZGP1 expression indicating high metastatic potential in tumor cells." (PMID 41535762, 2026). "The results indicate that patients with low AZGP1 expression have higher tumor stages, greater tumor malignancy, and are more likely to have metastases, with significantly worse outcomes compared with patients with high AZGP1 expression." (PMID 41535762, 2026). "In conclusion, our study identifies EHMT2 as a cell-extrinsic driver of tumor growth that largely works via suppressing NK cell-mediated anti-tumor immunity, primarily through the repression of AZGP1 and activation of the TGF-β1." (PMID 41366520, 2026). "AZGP1 likely exerts heterotypical effects on cells in the tumor microenvironment, such as stromal and endothelial cells." (PMID 38659028, 2024). "In this study, we aimed to overcome the limitations of existing CCA treatments by studying AZGP1 as a novel therapeutic target or diagnostic biomarker in CCA and demonstrated that AZGP1 acts as a tumour suppressor in CCA." (PMID 38183356, 2024). "We evaluated the effect of AZGP1 on cell proliferation in LuCaP147 spheroids derived from a PDX tumor." (PMID 38659028, 2024). "Tumour growth and size were significantly lower in the doxycycline‐induced AZGP1 expression groups than in the vehicle‐treated groups." (PMID 38183356, 2024). "Previous studies have revealed that AZGP1 fulfills its tumor suppression function by regulating the PTEN/AKT pathway, but the mechanism is unclear." (PMID 36831602, 2023). "Multivariate Cox analysis revealed that tumor differentiation and AZGP1 level were independent predictors of OS in patients with ICC (p < 0.05); RFS was independently associated with AZGP1 (p < 0.05) in patients with ICC." (PMID 37669935, 2023). "As important cell adhesion‐correlated genes, AZGP1 served as a tumor suppressor in PAAD by inducing EMT." (PMID 37506150, 2023).
tumor (continued). "In the present study, we investigated the predictive value of AZGP1, which was assessed by applying IHC to tumor tissue samples from men with locally advanced or metastatic PCa commencing ADT as the primary treatment." (PMID 32726925, 2020). "A meta-analysis has demonstrated that low AZGP1 expression in tumor tissue is an independent predictor of the time to biochemical failure following radical prostatectomy." (PMID 32726925, 2020). "Several genes involved in the immune system were identified as deregulated in both studies, such as interleukins, chemokines, APLN, TNFRSF11B, TNFS9, TCF7, AZGP1, strengthening the role of tumour extracellular environment alterations in the CRC biology." (PMID 31949199, 2020). "Zinc-alpha-2-glycoprotein (AZGP1) is a protein that is known to have a role in different tumor entities." (PMID 30813269, 2019). "Further work is needed to elucidate the co-localization of Zn with AZGP1 in the cytoplasm of tumor cells." (PMID 31740720, 2019). "AZGP1 was also identified as an important factor in regulating tumor carcinogenesis, including lung, prostate, breast, liver and gastrointestinal tumor 7-12." (PMID 31632499, 2019). "While increased Zn and AZGP1 secretion into the serum have been found in different human epithelial malignancies, we found for the first time that both Zn and AZGP1 levels were increased in the cytoplasmic compartment of HPV-positive OPSCC tumor cells." (PMID 31740720, 2019). "First, we confirmed AZGP1 expression was higher in a set of 28 tumor tissues than in normal colonic mucosa tissues by real-time quantitative PCR and western blot in a Chinese population." (PMID 25561225, 2014). "The AZGP1 mRNA levels were significantly reduced in 28 (80%) tumor tissue samples compared with the matched adjacent non-tumor tissue samples (P = 0.023)." (PMID 23935945, 2013). "Recently, it has been shown that AZGP1 is also involved in carcinogenesis and tumor differentiation." (PMID 23935945, 2013). "Based on this model, the tumor location, AZGP1 expression levels, T stage and N stage of the tumor were confirmed as independent prognostic factors." (PMID 23935945, 2013). "AZGP1 has a high level of amino-acid sequence homology with tumor-derived lipid-mobilizing factor, and in a mouse model of AZGP1-producing tumors, AZGP1 stimulated lipolysis in adipocytes leading to cachexia." (PMID 23935945, 2013). "Our study indicated that AZGP1 expression was significantly reduced at both the mRNA and protein levels in tumor tissue samples, compared with expression in matched adjacent non-tumor tissue samples." (PMID 23935945, 2013). "Clinicopathological analysis showed that the reduced expression of AZGP1 was significantly correlated with tumor location (P = 0.011), histological grade (P = 0.005) and T stage (P = 0.008)." (PMID 23935945, 2013). "AZGP1 is a member of macroglobulin family, which is actively involved in both inhibition of tumor growth and proliferation." (PMID 22625427, 2012). "AZGP1 has been reported to inhibit the proliferation of tumor cells by down-regulating cdc2 so as to lead to a cell cycle arrest in G2/M phase." (PMID 22625427, 2012). "AZGP1 was reported to inhibit the enzyme-mediated tumor invasion and activate apoptosis though binding hydrolases." (PMID 22625427, 2012). "We found that the inhibition of EHMT2 in tumor cells increased AZGP1, which reduced TGF-β1 levels." (PMID 41366520, 2026). "To investigate how low AZGP1 expression mediates tumor metastasis, we performed an in depth analysis of single-cell data and identified significant differences in the metabolic profiles of metastatic versus non-metastatic tumor cells, particularly in glycolysis." (PMID 41535762, 2026).